APOE (apolipoprotein E)
Diseases named in the same sentence as APOE in open-access papers (continued):
Sharing a sentence is not in itself a finding about the gene and the disease.
Hepatic steatosis (continued). "In this study, we try to answer above questions and intend to investigate the exact expression of adiponectin in HF-fed ApoE−/− mice and whether BSKS can target on liver adiponectin resistance to attenuate the degree of hepatic steatosis in ApoE−/− mice." (PMID 30894877, 2019). "Additionally, it has been established that betaine-elicited inhibition of CHDH and activation of BHMT can collectively enhance catabolism, but decrease the synthesis of betaine in the liver in ApoE−/− mice with hepatic steatosis." (PMID 25010553, 2014). "ApoE−/− mice is characterized by lipid accumulation and the development of hepatic steatosis." (PMID 23497035, 2013). "In humans, the impact of apoE on hepatic steatosis varies among different apoE isoforms." (PMID 23554788, 2013). "It has been observed that APOE may influence liver function and drug metabolism by modifying hepatic steatosis and transaminase activity." (PMID 22482072, 2012). "Indeed, rmSIRT1 reduced both hepatic steatosis and atherosclerotic phenotype in the ApoE−/− mice, therefore our study might be a first step towards establishing circulating SIRT1 as a potent therapeutic against the global lipid burden." (PMID 40653676, 2025). "Furthermore, elevated SFs density leads to impaired brain cognitive performance of naturally aged mice and hepatic steatosis in APOE−/− mice, and treatment with propranolol hydrochloride or 6OHDA reverses the SNS hyperactivity that causes these adverse outcomes." (PMID 33390926, 2020). "Using Apolipoprotein E knockout (ApoE−/−) mice on a western diet (WD), a mouse model of non-alcoholic fatty liver disease (NAFLD), we recently demonstrated that e-cigarettes containing nicotine trigger great oxidative stress, activate hepatocyte apoptosis, and cause hepatic steatosis." (PMID 31214115, 2019). "We found strong correlations between genetic effects on HCC and hepatic steatosis (r2 = 0.75), and HCC and cirrhosis (r2 = 0.69), whereas only three loci (APOE, HFE, and TERT) had concordant effects on HCC and biliary tract cancer." (PMID 40823170, 2025). "It has been shown that ApoE KO male mice at 12 months of age have increased serum levels of TAG, glucose, and insulin in addition to hepatic steatosis and increased plasma levels of liver enzymes, demonstrating liver damage." (PMID 37372993, 2023). "Our study is the first to show that melatonin alleviates the disturbance of PM2.5-triggered hepatic steatosis and liver damage by regulating the ROS-mediated PTP1B and Nrf2 signalling pathways in ApoE−/− mice." (PMID 35720187, 2022). "We elected to use ApoE−/− mice, as these animals, when fed a WD with 45% fat, as opposed to a very HFD with 60% of calories derived from fat develop hepatic steatosis." (PMID 31214115, 2019). "In contrast to the APOE genotype, the level of plasma APOE is not a significant explanatory variable of hepatic steatosis in our mice (R2=0.4141, p=0.168)." (PMID 37450924, 2024). "Despite the lack of significance in the present study, it cannot be ruled out that the concentration of plasma APOE affects the development of fatty liver disease." (PMID 37450924, 2024). "Dairy cows with fatty liver had reduced mRNA and protein abundance of APOB100, APOE, and MTTP." (PMID 37796906, 2023).
Hepatic steatosis (continued). "In agreement with the notion that saringosterol has a selective action for LXRβ, unlike pan-LXR agonist T0901317, we found that saringosterol treatment did not exacerbate hepatic steatosis in atherosclerotic ApoE−/− mice." (PMID 34564147, 2021). "Liver inspection after dissection also revealed a pale white color with fibrous consistency in all HFD-fed apoE−/− mice, absent in normal-diet-fed apoE−/− mice, suggestive of hepatic steatosis." (PMID 30538613, 2018). "Wt mice fed a WD and ApoE−/− mice under normal chow did not develop hepatic steatosis and adiposity, while ApoE−/− mice under WD did." (PMID 26263022, 2015). "In our study, after the NLX treatment, we did not observe changes in hepatic steatosis in the histological examination; however, at the molecular level, we observed a significant decrease in Fabp4 mRNA expression in the livers of the ApoE−/− mice (fold change 0.8)." (PMID 40868056, 2025). "Using Apolipoprotein E knockout (ApoE−/−) mice on a western diet (WD), a mouse model of non-alcoholic fatty liver disease (NAFLD), we recently demonstrated that nicotine in e-cigarettes activates hepatocyte apoptosis, and causes hepatic steatosis." (PMID 31214115, 2019). "In addition to the induction of fatty liver disease, LXR activation is also involved in RCT, which is initiated by cholesterol removal from cells to HDL or to lipid-free apolipoproteins, such as apoAI or apoE." (PMID 31976003, 2019). "Transgenic mice overexpressing the 11β-HSD1 gene selectively in the liver under the transcriptional control of the human apoE gene, exhibit fatty liver (but not steatohepatitis) with increased hepatic triglyceride accumulation and impaired hepatic lipid clearance." (PMID 22363403, 2012). "VSL#3 intervention failed to modulate the liver steatosis score in ApoE−/− mice, but completely reverted the progression of liver inflammation and fibrosis in ApoE−/− mice exposed to DSS (p<0.05; n = 8–12), and reduced the liver content of TNFα, RANTES, ICAM-1, and MIP-1α (p<0.05; n = 5)." (PMID 23029000, 2012). "ApoE−/− mice receiving WD showed abnormal glucose tolerance, hepatomegaly, weight gain and full spectrum of NASH including hepatic steatosis, fibrosis and inflammation, with no sign of renal damage." (PMID 26263022, 2015).
cerebral amyloid angiopathy (114 papers, 2011 to 2026). "Apolipoprotein E (ApoE) genotyping has long been of interest, as the ε4 allele represents the strongest genetic risk factor for sporadic Alzheimer’s disease and for cerebral amyloid angiopathy." (PMID 41102550, 2025). "Regarding APOE genotype, both the APOE ε2 and ε4 alleles are known to be strongly associated with cerebral amyloid angiopathy (CAA)." (PMID 40589441, 2025). "APOE plays a critical role in determining the risk and severity of cerebral amyloid angiopathy, which is characterized by the accumulation of amyloid-beta." (PMID 41035826, 2025). "This is attributed to the association of ApoE-ε4 with Aβ accumulation in cerebral amyloid angiopathy (CAA), which compromises the integrity of neurovascular units, leading to immune dysregulation and the induction of ARIA and microhemorrhages." (PMID 40290431, 2025). "The differential impact of ApoE isoforms on AD risk involves ApoE4’s detrimental effect and ApoE2’s protective role regarding Aβ severity, plaque burden, and cerebral amyloid angiopathy (CAA)." (PMID 38920542, 2024). "The traditional neuropathological manifestations associated with the APOE genotype include a greater accumulation of Aβ plaques and more pronounced cerebral amyloid angiopathy in individuals carrying the APOE ε4 allele." (PMID 37995081, 2024). "APOE impacts cerebrovascular disease as well: cerebral amyloid angiopathy (CAA), which is modulated by APOE4, increases risk for lobar intracranial hemorrhage (ICH), the severity of which is impacted by APOE2." (PMID 38502340, 2024). "The role of APOE4 in amyloid plaque formation in the brain parenchyma and vessel walls (cerebral amyloid angiopathy) has been repeatedly studied, and several studies suggest that the binding of APOE to Aβ is implicated in Aβ aggregation." (PMID 36835187, 2023). "While the exact pathophysiology giving rise to ARIA is unclear, the APOE ε4 allele is a risk factor for cerebral amyloid angiopathy (CAA) and microhemorrhage found in postmortem human studies." (PMID 36611492, 2022). "When APOE ε4 is expressed, β-amyloid aggregates in the brain, and amyloid plaques can cause cerebral amyloid angiopathy." (PMID 32466754, 2020). "APOE genotype plays a crucial role in determining the risk and severity of cerebral amyloid angiopathy (CAA), a common form of cerebral SVD characterized by accumulation of amyloid-β (Aβ) in the CNS leptomeningeal medium and small arteries." (PMID 32954261, 2019). "Genetic studies have proven apolipoprotein E (APOE) ε2 allele one allele of the principal cholesterol carrier in the brain can promote vasculopathy in cerebral amyloid angiopathy and HE in ICH." (PMID 29179524, 2017). "APOE is considered a strong risk factor for cerebral amyloid angiopathy and it is for a large part via this underlying etiology that APOE relates with intracerebral hemorrhage [27••]." (PMID 22538431, 2012). "Alterations of vessel structure have indeed been postulated to account for some findings in hemorrhage expansion, such as the effect of the apolipoprotein E ε2 allele on growth of cerebral amyloid angiopathy-related ICH." (PMID 23119028, 2012). "Therefore, precise risk management based on APOE genotyping and the presence of cerebral amyloid angiopathy and cerebral microbleeds should be performed before therapy is initiated." (PMID 41096797, 2025). "Notably, the APOE gene’s ε4 allele is a significant risk factor for late-onset AD and is associated with an elevated risk of cerebral amyloid angiopathy and age-related cognitive decline, even during the normal aging process." (PMID 39246604, 2024). "Mediation analyses were conducted to assess the indirect association of APOE-ε4 with cognition through AD-pathology, lacunar infarcts, hyaline arteriosclerosis, cerebral amyloid angiopathy (CAA), Lewy body disease (LBD), and TAR DNA-binding protein 43 (TDP-43)." (PMID 38115150, 2023).
cerebral amyloid angiopathy (continued). "Besides parenchymal amyloid plaque deposition, APOE4 has also been linked to cerebral amyloid angiopathy (CAA) formation in an AD transgenic mouse model (Tg2576) cross-bred with humanized APOE-knock in mice." (PMID 36153580, 2022). "Interestingly, research has shown that both the APOE*2 and APOE*4 alleles increase the risk of cerebral amyloid angiopathy (CAA) by encouraging accumulation of Aβ in the cerebral vasculature." (PMID 24829845, 2014). "Additionally, ApoE4 mice model the known association in humans between AD (and cerebral amyloid angiopathy, CAA) and possession of the apolipoprotein E ε 4 allele (ApoE4)." (PMID 25191214, 2014). "APOE E2, E3, and E4 alleles alter the likelihood of developing AD and cerebral amyloid angiopathy." (PMID 21933389, 2011). "The HAE-4 antibody, developed at Washington University, binds aggregated APOE found in amyloid plaques and cerebral amyloid angiopathy in APOE4-expressing mice." (PMID 40943807, 2025). "This suggests that the effect of APOE ε4 on cognition for a substantial part was due to cerebral amyloid angiopathy." (PMID 40344552, 2025). "On the one hand, APOE ɛ4 carriers probably have a higher prevalence of cerebral amyloid angiopathy with vascular Aβ accumulation." (PMID 41451854, 2025). "The APOE ε4 variants are well-established genetic risk factors for ICH related to cerebral small vessel disease, particularly in the context of cerebral amyloid angiopathy." (PMID 38363572, 2024). "This study identified cerebral amyloid angiopathy, commonly observed in APOE ε4 carriers and known for increasing intracerebral hemorrhage risk, as a potential mediator in this association." (PMID 38363572, 2024). "We advocate that patients should be screened for cerebral amyloid angiopathy using the Boston criteria and undergo APOE genotyping prior to treatment." (PMID 38086820, 2023). "Studies using APOE knock-in and transgenic mice have demonstrated a strong isoform-dependent effect of apoE on the accumulation of amyloid-β (Aβ) deposition in the brain in the form of both Aβ-containing amyloid plaques and cerebral amyloid angiopathy." (PMID 31623648, 2019). "APOE-ε4 has been shown to adversely affect this HDLC-Aβ interaction and has been implicated as a risk factor for cerebral amyloid angiopathy, another prominent pathologic hallmark of AD." (PMID 30856540, 2019). "Conversely, cerebral amyloid angiopathy and insulin like growth factor binding protein 5 (IGFBP5) were only associated with APOE/TOMM40 SNPs (right lane), suggesting that the genetic effects of 457 SNPs on these variables are contingent on APOE/TOMM40." (PMID 30349450, 2018). "The association with cerebral amyloid angiopathy was attenuated by increasing the number of SNPs in the AD-PRS, indicating that it is subjected to monogenic influence from APOE/TOMM40 SNPs." (PMID 30349450, 2018). "By showing that APOE ε4 was associated with a significant increase in ICH risk in this specific population of patients, our findings support further research aimed at evaluating the role of cerebral amyloid angiopathy in brain AVM carriers." (PMID 38363572, 2024). "The APOE protein plays a significant role in the metabolism of Aβ since it exerts a pronounced influence on the deposition of Aβ, leading to the formation of senile plaques and the development of cerebral amyloid angiopathy (CAA)." (PMID 37995081, 2024). "In addition, the SUVR values were also not explained by sex (female/male), age at diagnosis (before/after 65 years), APOE phenotype or to the presence of cerebral amyloid angiopathy." (PMID 37588670, 2023). "APOE status was also highly correlated with cerebral amyloid angiopathy (CAA)." (PMID 35806110, 2022).
cerebral amyloid angiopathy (continued). "In AD patients, astrocytes and microglia react with Aβ plaques, cerebral amyloid angiopathy-laden arteries and capillaries, as well as neurofibrillary tangles, and therefore activate transcription of APOE in microglia, down-regulation in astrocytes, and dysregulation of lipid metabolism." (PMID 36138870, 2022). "The post-mortem neuropathological factors correlated with the APOE genotype are a higher Aβ plaque burden and more severe cerebral amyloid angiopathy in APOE ε4 carriers, also confirmed by Aβ Positron Emission Tomography imaging across preclinical and clinical AD stages." (PMID 34572474, 2021). "Similarly, the APOE genotypes in AD greatly affect the amyloid beta (Aβ) deposition to form senile plaques and result in cerebral amyloid angiopathy." (PMID 33192461, 2020). "For ICH located in the lobar regions of the brain, the epsilon 2 variant within apolipoprotein E (APOE), a well-studied risk factor for ICH via cerebral amyloid angiopathy, has been shown to increase both the volume of the hematoma and the risk of poor outcome." (PMID 31519204, 2019). "This suggests that APOE ε4 may affect the occurrence of ARIA through a dual mechanism—both by exacerbating the severity of cerebral amyloid angiopathy (CAA) and by amplifying the blood-brain barrier disruption effect through apolipoprotein E-mediated inflammatory responses." (PMID 40308765, 2025). "Apolipoprotein E (APOE) ε4 is a well-known genetic risk factor for ICH among persons without AVM, and cerebral amyloid angiopathy is a vasculopathy frequently observed in APOE ε4 carriers that may increase the risk of ICH." (PMID 38363572, 2024). "However, a dilemma is that the apoE isoform specific restriction to arteries may lead to the development of cerebral amyloid angiopathy (CAA), vascular dementia and AD." (PMID 27931262, 2016). "Vascular Aβ deposition has been shown to be related to pericytes in AD and cerebral amyloid angiopathy (CAA), and vascular Aβ deposition is dependent on APOE isoform, with an APOE4 > APOE3 > APOE2 trend." (PMID 39394110, 2024). "Human APOE exists in one of three major isoforms (E2, E3, and E4), where the APOE4 genotype enhances the deposition of beta-amyloid-forming senile plaques and cerebral amyloid angiopathy (CAA)." (PMID 37891895, 2023). "The occipital cortex, the only cortical region showing cerebral amyloid angiopathy (CAA), exhibited a distinctive chronic inflammatory microglial profile and lower APOE expression." (PMID 35838824, 2022). "Female and male mice were assayed for general cerebral fibrillar and pyroglutamate (pGlu-3) Aβ deposition, cerebral amyloid angiopathy (CAA), microhemorrhages, apoE and cholesterol composition, astrocytes, microglia, inflammation, lysosomal dysfunction, and neuritic dystrophy." (PMID 38891941, 2024). "It has been reported that reduction of fibrillar amyloid plaques via astrocytic-APOE knockout, but not microglial-APOE knockout, results in a shift towards formation of cerebral amyloid angiopathy (CAA)." (PMID 39528861, 2024). "The distribution of the SUVR values was independent of sex, APOE phenotype, early and late onset of symptoms and the presence of cerebral amyloid angiopathy." (PMID 37588670, 2023). "We hypothesize that apoE and apoE isoforms play a role in modulating WMH via apoE isoform-dependent effects on oxylipins and 7-ketocholesterol, as well as amyloid related vascular injury, as seen in cerebral amyloid angiopathy." (PMID 37275347, 2023). "It was found that both APOE and CLU could delay the initiation time of amyloid growth kinetics in a concentration-dependent manner, acting as extracellular chaperones to inhibit amyloid-β deposition in patients with sporadic cerebral amyloid angiopathy." (PMID 33521130, 2021).
cerebral amyloid angiopathy (continued). "Similarly, an increased frequency of APOE ε2 have been reported in argyrophilic grain disease and hemorrhage in cerebral amyloid angiopathy, suggesting APOE ε2 may play a unique role in the non-AD pathological processes implicated in SNAP." (PMID 29190651, 2017).